CFTR (CF transmembrane conductance regulator)
Diseases named in the same sentence as CFTR in open-access papers (continued):
Sharing a sentence is not in itself a finding about the gene and the disease.
enteropathy (2 papers, 2019). "Altogether, these results suggest that the genistein-mediated potentiation of CFTR channel activity might be taken advantage to treat the gliadin-induced enteropathy." (PMID 30981209, 2019).
eosinophilia (2 papers, 2021 to 2024). "Long-term azithromycin therapy; bacterial bronchial colonization; use of high-dose inhaled corticosteroids; genetic factors such as CFTR gene mutations and the presence of atopy and eosinophilia have been reported to increase the risk of ABPA." (PMID 34174797, 2021). "Thus, in CF, CFTR-dependent altered regulation of T-cell cytokine secretion leads to a shift toward a pro-inflammatory state and a predominant Th2 response with exaggerated immunoglobulin E (IgE) levels, peripheral eosinophilia, and pulmonary infiltrates, a predisposition for ABPA." (PMID 39330416, 2024).
Familial adenomatous polyposis (2 papers, 2020 to 2021). Familial adenomatous polyposis (FAP) is characterized by the development of hundreds to thousands of adenomas in the rectum and colon during the second decade of life. "For example, a physician or genetic counselor may recommend carrier testing of a prospective parent for a mutation in the CFTR gene associated with cystic fibrosis or testing for mutations in the APC gene for a member of a family with a history of familial adenomatous polyposis (FAP)." (PMID 32342786, 2020).
female infertility (2 papers, 2018 to 2025). Diminished or absent ability of a female to achieve conception. "Although the causes are unknown, female infertility in CF is linked to the expression of CFTR on the epithelial cells of the cervix." (PMID 41010724, 2025). "Clinical sensitivity was assessed with samples containing variants representative of male and female infertility, and it was 100% for SNVs/indels, CFTR IVS8-5T variants, sex chromosome aneuploidies, and copy number variants (CNVs) and > 93% for Y chromosome microdeletions." (PMID 29779145, 2018). "The causes of female subfertility are still to be defined, but since the female anatomy does not change, defects in the CFTR protein impair cervical mucus pH and viscosity." (PMID 41010724, 2025).
Gilbert syndrome (2 papers, 2024). An autosomal recessive inherited disorder characterized by unconjugated hyperbilirubinemia, resulting in harmless intermittent jaundice. "This comprehensive approach aims to optimize therapy management and improve outcomes for pwCF receiving CFTR modulator therapy and concurrent Gilbert Syndrome." (PMID 38956524, 2024). "Physicians should be vigilant regarding factors influencing therapy tolerance in these patients, underscoring the need for further research to fully elucidate the interaction between Gilbert syndrome and CFTR modulator therapy." (PMID 38956524, 2024). "Persistent isolated increase of bilirubin after ETI have demasked Gilbert’s syndrome in some cases after initiation of CFTR-modulator therapy." (PMID 38717689, 2024).
Hepatitis (2 papers, 2022 to 2025). Inflammation of the liver. "CFTR drug-dose-related adverse effects (e.g., hepatitis, rash and other skin lesions, gastrointestinal problems for some caftors), or DDI issues could also be addressed." (PMID 36015300, 2022).
Hyponatremia (2 papers, 2024 to 2025). An abnormally decreased sodium concentration in the blood. "A defective cystic fibrosis transmembrane conductance regulator (CFTR) protein can lead to excessive losses of sodium and chloride in sweat, which results in hypochloremia and hyponatremia." (PMID 38794273, 2024). "Researchers found that changes to the cystic fibrosis transmembrane conductance regulator (CFTR) protein can affect the movement of Na+ and Cl− in fluid-secreting cells, resulting in conditions such as dehydration, hyponatremia, and hypokalemia due to fluctuations in sweat ion concentrations." (PMID 41228776, 2025).
intrahepatic cholestasis (2 papers, 2016 to 2021). A cholestasis characterized by impairment of the bile flow caused by obstruction located in the liver. "Therefore, we suggest that SLC25A13 should be compulsory after CFTR, which causes the most common AR genetic disorder in white population, in every panel for children with intrahepatic cholestasis." (PMID 27706244, 2016).
liver failure (2 papers, 2021 to 2024). A liver disease characterized by the liver losing or has lost all of its function. "These patients were characterized by hepatobiliary disease, which in one of them was severe eventually leading to lethal liver failure, indicating CFTR-dup2 association with a more severe CF phenotype." (PMID 34600583, 2021). "Patients with severe liver failure (Child–Pugh class C) should refrain from CFTR modulator treatment, given the absence of clinical studies." (PMID 38473009, 2024).
malignant glioma (2 papers, 2020 to 2023). A grade III or grade IV glioma arising from the central nervous system. "While CFTR has been implicated in cancer development, the role of CFTR in non‐epithelium cell‐derived tumours, like malignant gliomas, is completely unknown." (PMID 32463592, 2020). "To answer this question, we examined the protein expression levels of CFTR in a cohort of tissue microarray samples which include 5 cases of normal cerebellum and 20 cases of malignant gliomas using immunochemical staining." (PMID 32463592, 2020). "The result demonstrated that CFTR was expressed in all malignant glioma cell lines, whereas the expression levels of CFTR were higher in SW1783 and SW1088 than that in U87 and U138." (PMID 32463592, 2020). "Malignant gliomas are the most common and aggressive intracranial tumours; however, the role of CFTR in the development of malignant gliomas is unclear." (PMID 32463592, 2020). "Therefore, we undertook the present study to determine the role of CFTR in malignant gliomas using cell lines, xenograft mouse models and human samples." (PMID 32463592, 2020). "Here, we report that CFTR is expressed in malignant glioma cell lines." (PMID 32463592, 2020). "In addition, we have unveiled a tumour promoting role of CFTR in malignant gliomas via up‐regulation of Akt/Bcl2‐mediated anti‐apoptotic pathway." (PMID 32463592, 2020). "The present study has demonstrated that CFTR is expressed in malignant gliomas." (PMID 32463592, 2020). "The expression level of CFTR in malignant glioma is higher than that in normal brain." (PMID 32463592, 2020).
Miscarriage (2 papers, 2014 to 2024). A pregnancy that ends at a stage in which the fetus is incapable of surviving on its own, defined as the spontaneous loss of a fetus before the 22th week of pregnancy. "Overexpression of CFTR and inadequate expression of ENaC-α was observed in the decidua from abortion-prone mice and women who had a miscarriage." (PMID 24914548, 2014). "Compared to normal decidua samples from mice and humans, CFTR expression was higher and ENaC-α expression was weaker in the mouse abortion-prone and human miscarriage samples." (PMID 24914548, 2014). "Therefore, cytokines INF-γ and TNF-α should be responsible for altered expression of CFTR and ENaC-α in decidua of miscarriage." (PMID 24914548, 2014). "Similarly, ENaC-α protein expression in human miscarriage samples was lower than that in normal pregnancy samples (P<0.05), while CFTR protein expression was higher (P>0.05)." (PMID 24914548, 2014). "Similarly, increased CFTR and decreased ENaC-α mRNA expression was found in the human decidua samples of miscarriage compared to decidua samples from normal pregnancies (0.58±0.04 vs. 1.19±0.09 and 1.47±0.12 vs. 0.42±0.07 respectively; P<0.01)." (PMID 24914548, 2014). "Thus, the precise expression levels of CFTR and ENaC-α in human miscarriage remain to be explored." (PMID 24914548, 2014). "However, the up-regulation of CFTR and down-regulation of ENaC-α in mechanism of miscarriage remains unclear." (PMID 24914548, 2014). "The abnormal expression of CFTR and ENaC-α might disrupt the cellular microenvironment that is harmful for embryo implantation or maintain of pregnancy; or might result from degeneration or necrosis of decidua as a consequence of miscarriage." (PMID 24914548, 2014). "Therefore, the aim of this study was to investigate the expression of CFTR and ENaC-α in the CBA×DBA/2 model and in clinical cases of early miscarriage in order to determine its potential significance in miscarriage." (PMID 24914548, 2014). "However, it is not clear whether the expression levels of CFTR and ENaC-α in the decidual component during early pregnancy are related with early miscarriage." (PMID 24914548, 2014).
Myocardial fibrosis (2 papers, 2021 to 2023). "Chronic inflammation is not the only trigger for myocardial dysfunction, as chronic hypoxia, myocardial fibrosis, and cardiomyocyte contraction regulation linked to the CFTR also seem to play a role." (PMID 36678185, 2023). "Just like epithelial CFTR, cardiac CFTR also conducts Cl-, and loss of its function influences myocyte contractility, intracellular calcium signaling, myocardial fibrosis, and heart remodeling." (PMID 34513358, 2021). "Severe CFTR genotypes such as ΔF508: ΔF508 and the asparagine-to-lysine mutation at position 1303 (N1303K) may be associated with the development of myocardial fibrosis and necrosis." (PMID 36678185, 2023). "Severe CFTR genotypes, such as ΔF508: ΔF508 and asparagine-to-lysine mutation at position 1303 (N1303K) mutations may be associated with the development of myocardial fibrosis and necrosis." (PMID 34513358, 2021). "Thus, myocardial fibrosis may result from the co-occurrence of genetic susceptibility to myocardial lesions (severe CFTR genotypes along with the presence of certain modifying genes) and a deficiency of some trophic factors essential for myocardial metabolism." (PMID 34513358, 2021). "Thus, myocardial fibrosis may result from the deficiency of trophic factors essential for myocardial metabolism against the background of genetic susceptibility to myocardial damage (severe CFTR genotypes together with the presence of certain modifying genes)." (PMID 36678185, 2023).
neurofibromatosis type 1 (2 papers, 2018 to 2020). A clinically heterogeneous, neurocutaneous genetic disorder characterized by cafe-au-lait spots, iris Lisch nodules, axillary and inguinal freckling, and multiple neurofibromas. "This is the first report of a Neurofibromatosis type 1 patient with pancreas divisum and multiple periampullary tumors harboring pathogenic germline variants in NF1 and CFTR genes." (PMID 32425982, 2020). "In this study, we describe for the first time a Neurofibromatosis type 1 patient with pancreas divisum, multiple periampullary tumors and germline pathogenic variants in NF1 and CFTR genes." (PMID 32425982, 2020).
ovarian hyperstimulation syndrome (2 papers, 2023). A complication of ovulation induction in infertility treatment. "Increased estrogen level during the ovarian hyperstimulation syndrome leads to upregulation of CFTR and enhanced CFTR channel activity." (PMID 36941680, 2023). "In rats, an increment of CFTR expression in the uterus and ovary was observed after induced ovarian hyperstimulation syndrome (OHSS), in which E2 levels were found to be eight times higher than normal levels." (PMID 37175587, 2023).
pancreatic ductal adenocarcinoma (2 papers, 2013 to 2021). An infiltrating adenocarcinoma that arises from the epithelial cells of the pancreas. "Molecular mechanistic study suggest loss of cystic fibrosis transmembrane conductance regulation (CFTR) and a corresponding increase in MUC4 expression is observed in about 81% of pancreatic ductal adenocarcinoma cell lines." (PMID 24454496, 2013).
periodontitis (2 papers, 2020 to 2026). An acute or chronic inflammatory process that affects the tissues that surround and support the teeth. "The elevated gingival CFTR expression in late-onset periodontitis is an important requirement for the exaggerated NET formation, as it enables the bicarbonate enrichment and alkalosis of gingival crevicular fluid." (PMID 33291407, 2020). "Moreover, CFTR expression in gingival epithelial from periodontitis biopsies is strongly elevated and even present in the gingival connective tissue." (PMID 33291407, 2020).
pneumococcal infection (2 papers, 2015 to 2024). Infections with bacteria of the species streptococcus pneumoniae. "Thus, it appears that the apparent susceptibility of CFTR–/– mice to mucoid pneumococcal infection is dependent on degree of mucoidy as measured by polysaccharide, but not on early recruitment of inflammatory cytokines." (PMID 26469863, 2015).
Polycystic Ovarian Syndrome (2 papers, 2017 to 2018). "CFTR regulates ovarian estrogen biosynthesis by amplifying the FSH-stimulated signal via the nuclear soluble adenylyl cyclase (sAC), defective CFTR-dependent regulation of estrogen production may underlie the ovarian disorders seen in CF and polycystic ovarian syndrome (PCOS)." (PMID 29930176, 2018).
polyp (2 papers, 2013 to 2023). A usually exophytic mass attached to the underlying tissue by a broad base or a thin stalk. "The expression and distribution of ionocytes and CFTR in nasal mucosa and polyp epithelium were observed." (PMID 36662267, 2023). "Under the microscope, the number of CFTR-0 and CFTR-1 cells in the nasal mucosa and polyp epithelium was the largest, while the number of CFTR-2 and CFTR-3 cells was small." (PMID 36662267, 2023). "Compared with the nasal mucosa and polyp epithelium, it was found that the expression of CFTR increased with the expansion of inflammation, especially in the polyp epithelium (P < 0.01)." (PMID 36662267, 2023).
Pseudomonas infection (2 papers, 2021 to 2024). Infections with bacteria of the genus pseudomonas. "Similarly, Pseudomonas infection and airway dysbiosis persist in pwCF on CFTR modulator therapy, providing a strong stimulus for neutrophilic inflammation." (PMID 39293854, 2024). "Finally, highly effective CFTR modulators have the potential to modify microbiome of patients with CF, at least for Pseudomonas infection." (PMID 34944110, 2021).
psoriasis (2 papers, 2022 to 2024). An autoimmune condition characterized by red, well-delineated plaques with silvery scales that are usually on the extensor surfaces and scalp. "On the contrary, polycystin, CFTR, TRPC, and CRAC channels in keratinocytes exert repressive roles on psoriasis development." (PMID 38474002, 2024).
respiratory syncytial virus infection (2 papers, 2020). "We previously demonstrated that the expression and function of the CFTR of 16HBE14o- cells (human bronchial epithelial cells) were inhibited under ozone exposure and respiratory syncytial virus infection." (PMID 32754261, 2020).
Rotavirus infection (2 papers, 2014 to 2017). Infection with any of the rotaviruses. "Krisanaklan was tested for antisecretory activity in a mouse model of CFTR-dependent secretory diarrhea caused by cholera toxin and of CaCC-dependent secretory diarrhea caused by rotavirus infection." (PMID 24551253, 2014).
sarcoglycanopathy (2 papers, 2020 to 2024). Deficiencies or mutations in the genes for the sarcoglycan complex subunits. "In our previous paper, incubation of cells, models of sarcoglycanopathy with a number of CFTR correctors, resulted in an increase of the mutated α-SG and the localization at the plasma membrane." (PMID 32155735, 2020). "In conclusion, our results strengthen the idea that CFTR correctors, acting probably as proteostasis modulators, have the potential to progress as therapeutics for sarcoglycanopathies caused by missense mutations." (PMID 32155735, 2020). "Still open questions of this strategy are the mechanism of action of CFTR correctors in sarcoglycanopathy, the evaluation of possible side effects, and the broadness of efficacy in a single subtype and all four subtypes of sarcoglycanopathy." (PMID 39769077, 2024). "In conclusion, our data are indicative that CFTR correctors, in particular C17, may have a broad application and should become a valid therapeutic option for sarcoglycanopathy." (PMID 39769077, 2024). "Finally, even if a deeper investigation on the mechanism of action of CFTR correctors is mandatory, our findings represent a first crucial step towards the development of a remedy for most of the sarcoglycanopathy patients." (PMID 32155735, 2020).
SARS-CoV infection (2 papers, 2011 to 2022). "Three different resequencing microarrays were analysed using ResqMi: 'CFTR' (targeting the human CFTR gene), 'SARS' (for the Corona virus causing Severe Acute Respiratory Syndrome), and 'Mito' (which became the Affymetrix MitoChip v.1.0)." (PMID 22011414, 2011). "As a result of these pleiotropic effects, in vivo inhibition of miRNA-223-3p reduced pulmonary histopathology, suggesting that the impact of silencing anti-inflammatory targets, such as CFTR, was dominant over pro-inflammatory targets, which are highly dysregulated in SARS-CoV infection." (PMID 35229638, 2022).
Sepsis (2 papers, 2014 to 2020). Sepsis is defined as life-threatening organ dysfunction caused by a dysregulated host response to infection. "Considering that PAF-AH is a limiting enzyme for hydrolyzing PAF and plasma PAF-AH could limit the development of sepsis, we designed experiments to test whether inhibition of PAF-AH affect LPS-induced lung inflammation in the CFTR-deficient mice." (PMID 24671173, 2014).
skin cancer (2 papers, 2022 to 2025). "The prevalence of skin cancers in our CFTR cohort was also higher compared to the overall AGP cohort suggesting that CFTR PVs may increase skin cancer risk." (PMID 41147257, 2025).
Thrombocytopenia (2 papers, 2013 to 2014). A reduction in the number of circulating thrombocytes. "Blood platelet counts were markedly lower in pneumonic F508del mice than wildtype, suggesting that CFTR deficiency promotes thrombocytopenia during acute lung infection." (PMID 24671173, 2014). "Mutation of CFTR causes severe thrombocytopenia in a LPS-induced lung inflammation mouse model." (PMID 24671173, 2014). "We have reported that blocking PSGL-1, PAF, or rectifying trafficking of mutated CFTR in F508del mice could lessen thrombocytopenia and alveolar neutrophil transmigration in the LPS-challenged F508del mice." (PMID 24671173, 2014). "In this study, for the first time, we found that inhibition of CFTR could mimic CFTR mutation to promote thrombocytopenia during lung infection." (PMID 24671173, 2014). "Correction of thrombocytopenia by anti-platelet aggregation, blockade of PSGL-1 or PAF receptor, or rectifying of mutated CFTR trafficking is associated with a better outcome of acute lung inflammation." (PMID 24671173, 2014). "More importantly, our data have supported that correction of the F508del CFTR trafficking are able to counteract the proinflammatory phenotype of F508del platelets and neutrophils, reflected by attenuation of thrombocytopenia, reduction of BAL neutrophils, protein, and MIP-2 levels." (PMID 24367540, 2013). "Attenuation of thrombocytopenia by inhibiting platelet aggregation, depleting F508del neutrophils, blocking PSGL-1 or PAF, or rectifying of F508del CFTR trafficking in LPS-challenged F508del mice significantly diminished neutrophil transalveolar migration or lung inflammation." (PMID 24367540, 2013).
ulcerative colitis (2 papers, 2021 to 2022). An inflammatory bowel disease involving the mucosal surface of the large intestine and rectum. "In ulcerative colitis (UC) patients, KLF4, CFTR, BMP2, TLR2 showed significantly lower expression in UC-associated cancer." (PMID 35733095, 2022).